BMP2 (bone morphogenetic protein 2)
Diseases named in the same sentence as BMP2 in open-access papers (continued):
Sharing a sentence is not in itself a finding about the gene and the disease.
osteoarthritis (29 papers, 2007 to 2026). A noninflammatory degenerative joint disease occurring chiefly in older persons, characterized by degeneration of the articular cartilage, hypertrophy of bone at the margins and changes in the synovial membrane. "Concerning the serine protease HtrA1, another undesirable marker which was over-expressed in osteoarthritis and associated with chondrocyte dedifferentiation, interestingly, we unambiguously and originally demonstrated that BMP-2 induces its down-regulation." (PMID 28837082, 2017). "IL-1β, a pro-inflammatory mediator, and bone-regulatory factors, including BMP-2 (bone morphogenetic protein-2), promote articular cartilage damage and hasten osteoarthritis development by facilitating the release of various proteolytic enzymes." (PMID 36726968, 2022). "Nog serves as an inhibitor of bone morphogenetic proteins (BMPs) and prevents cartilage degeneration and osteoarthritis development by inhibiting Il1β and Bmp2 expression." (PMID 33407721, 2021). "The use of coacervate technology to deliver BMP2/sFLT1 with hMDSCs for cartilage repair holds promise for possible clinical translation into an effective treatment modality for osteoarthritis and traumatic cartilage injury." (PMID 31771623, 2019). "In healthy cartilage, BMP-2 is hardly present, whereas it is highly expressed during osteoarthritis." (PMID 17922907, 2007). "BMP-2 is rarely present in healthy cartilage, whereas it is highly expressed in osteoarthritis." (PMID 34945097, 2021). "BMP-2 and SP7 are two positive regulators of chondrocyte hypertrophy and are both reported to be upregulated in osteoarthritis cartilages." (PMID 35280506, 2022). "For example, considering the regulation between OP miRNAs and their targets BMP2 and SP1 in the ‘Osteoarthritis Pathway” and “TGF-beta signaling pathway,” BMP2 are functional in osteoblast differentiation." (PMID 32194637, 2020). "We further compared the in vivo articular cartilage repair of hMDSCs stimulated with BMP2 delivered through coacervate sustain release technology and lenti-viral gene therapy-mediated gene delivery in a monoiodoacetate (MIA)-induced osteoarthritis (OA) model." (PMID 31771623, 2019). "Microarray analysis data of ARV infected cells and σB transfected cells were validated by using primers of 4 important candidate genes (SPP1, BMP2, SMAD1 and IL1B) that were involved in osteoarthritis pathway." (PMID 29731966, 2018). "To address this issue, we focused our attention on the expression levels of molecules that were previously shown to be modulated during the onset of IVD degeneration or osteoarthritis (COL1A1, COL2A1, AGC1, BMP2, MMP13, MGP and P21)." (PMID 21726455, 2011). "The osteoporotic patients showed no mineralization response to bone morphogenetic protein 2 stimulation, while the osteoarthritis patients significantly responded to bone morphogenetic protein 2 stimulation." (PMID 31771161, 2019). "Our findings suggest, for the first time to our knowledge, that BMP-2-induced Wnt/β-catenin signaling activation through LRP-5 may contribute to chondrocyte hypertrophy and cartilage degradation in osteoarthritis." (PMID 22513174, 2012).
ovarian carcinoma (29 papers, 2006 to 2024). A malignant neoplasm originating from the surface ovarian epithelium. "We also show that BMP-2 expression in tumor tissues is associated with a poorer prognosis for ovarian cancer patients." (PMID 19366455, 2009). "In compare to the mesenchymal stromal cells (HOTC) of normal ovarian tissue, we have shown that mesenchymal like cancer tumor fibroblasts (HOCTC) sprouting from ovarian cancer tissue expressed higher levels of BMP2, BMP4 and TGF-β, which are highly associated with tumorigenesis and metastasis." (PMID 22330345, 2012). "Moreover, SMAD6 was reported to be overexpressed in ovarian adenocarcinoma compared to normal ovarian tissue, and expression of BMP-2 protein has been shown to induce SMAD6 expression in ovarian cancer cells and was associated with poor prognosis." (PMID 21984931, 2011). "In addition, we show that high expression of BMP-2 in ovarian cancer tissues is associated with shorter survival in patients." (PMID 19366455, 2009). "Finally the association between BMP-2 and ovarian cancer patient survival was examined using ovarian cancer tissue array analysis." (PMID 19366455, 2009). "This investigation showcased a comprehensive genome-wide methylation profile of epithelial ovarian cancer (EOC) and identified six hypermethylated/downregulated genes, (POLR3B, PLXND1, GIGYF2, CRKL, STK4, and BMP2) as potential diagnostic targets." (PMID 38627856, 2024). "Overexpression of BMP2, for example, correlated with poor survival outcomes in ovarian cancer; BMP2 enhanced the migration and invasion of ovarian cancer cells, suggesting that BMP signaling promotes tumor progression and metastasis." (PMID 36353620, 2022). "Despite this discrepancy, our results were in line with one study in ovarian cancer stem-like cells (CSCs), demonstrating that BMP2 was preferentially expressed in different CSC populations." (PMID 34244572, 2021). "We previously reported that BMP2 also increased sphere formation and migration of ovarian cancer cells." (PMID 34360647, 2021). "In fact, BMP2 activates phospho-SMAD signalling in ovarian cancer and is involved in triggering the epithelial-to-mesenchymal transition." (PMID 33685452, 2021). "BMP2 was detected to be involved in promoting the phospho-SMAD 1/5 protein levels in the SKOV3 cells (ovarian cancer cell line) and BMP2 inhibitor (Noggin) supressed this process." (PMID 33685452, 2021). "Molecular factors not included in our array, such as gp100, ERCC, CD44, CD147, c-met, IL-6, ALDH, CD117 and BMP2 have also been studied in the context of chemoresistance in ovarian cancer." (PMID 27258020, 2016). "For instance, SMAD5 expression is inversely correlated with the prognosis of serious ovarian cancer patients, and BMP-2 stimulated cellular proliferation by inducing phosphorylated SMAD5 (pSMAD5) translocation into the nucleus in ovarian cancer cells." (PMID 27661009, 2016). "For example, two separate studies in Ovarian cancer show copy number gains as frequent events, which we later determined to be due to amplifications in the BMP2 and BMP7 loci." (PMID 27114889, 2016). "MSC have been shown to contribute to ovarian cancer tumorigenicity through altered production of Bone Morphogenetic Protein (BMP2) leading to an increase of ovarian cancer cell (OCC) proliferation in vitro and in vivo." (PMID 22666502, 2012). "Altered secretion of BMP2 by MCs is able to increase the number of ovarian cancer stem cells and consequently stimulate ovarian tumor growth in an immuno-compromised mouse." (PMID 22666502, 2012). "In this study, BMP-2 was shown to be expressed in ovarian cancer, benign ovarian tumors, and normal ovarian tissue, and its expression in ovarian cancer was clearly lower than the latter two." (PMID 20587070, 2010).
ovarian carcinoma (continued). "The five-year survival rate after surgery of ovarian cancer patients with positive expression of BMP-2, BMPRIB, and BMPRII was remarkably higher than that of patients with negative expression of BMP-2, BMPRIB, and BMPRII." (PMID 20587070, 2010). "For instance, Kiyozuka and Le Page both detected the expression of BMP-2 in ovarian cancer tissues, and Kiyozuka further confirmed that BMP-2 was involved in the formation of serous ovarian cancer psammoma bodies." (PMID 20587070, 2010). "Le Page and colleagues have recently demonstrated that BMP2 treatment of several ovarian cancer cell lines also reduces the cell-cell cohesion during spheroid formation; however, evidence for the molecular mechanism was not presented." (PMID 20187934, 2010). "In order to investigate the influence of BMP-2 on the prognosis of ovarian cancer patients, 100 patients were followed up after their surgery." (PMID 20587070, 2010). "Here we investigate the effect of BMP-2 on several parameters of ovarian cancer tumorigenesis using the TOV-2223, TOV-1946 and TOV-112D EOC cell lines." (PMID 19366455, 2009). "Similar effects with BMP-4, as observed here with BMP-2, have recently been reported in ovarian cancer cell lines and ovarian cancer primary cultures." (PMID 19366455, 2009). "Further work needs to be done to define particular characteristic of each ovarian cancer cell line that determine response to BMP-2." (PMID 19366455, 2009). "The fact that patients with higher expression of BMP-2 in ovarian tissues have shorter survival supports a role for BMP-2 in the motility of ovarian cancer cells and aggressiveness of ovarian tumors." (PMID 19366455, 2009). "In our ovarian cancer cell lines, constitutive phosphorylation of Erk MAPKs was visible and a slight transient increase was induced in the cytoplasm after 20 min of BMP-2 treatment." (PMID 19366455, 2009). "An initial report highlighted the overexpression of BMP-2 in primary cultures of ovarian cancer cells and in the tissues of ovarian cancer patients." (PMID 19366455, 2009). "We previously observed the over-expression of BMP-2 in primary cultures of epithelial ovarian cancer (EOC) cells as compared to normal epithelial cells based on Affymetrix microarray profiling." (PMID 19366455, 2009). "To determine if BMP-2 stimulation leads to NF-κB activation through the Akt pathway in ovarian cancer cell lines, we examined the phosphorylation of Akt and p65 using a specific antibody that recognizes phosphorylated serine sites." (PMID 19366455, 2009). "First, we examined the biological role of BMP-2 on three novel ovarian cancer cell lines (TOV-2223, TOV-1946, TOV-112D)." (PMID 19366455, 2009). "In ovarian cancer, overexpression of BMP-2, BMP-4 and BMP-7 mRNAs have been reported as dysregulated by microarray analyses." (PMID 19366455, 2009). "To investigate the role of BMP-2 in ovarian cancer cells we selected three cell lines, TOV-2223, TOV-1946 and TOV-112D, for in vitro assays." (PMID 19366455, 2009). "Using three different cell lines, we report different in vitro and in vivo effects of BMP-2 on epithelial ovarian cancer cells." (PMID 19366455, 2009). "However, BMP signalling was seen to be upregulated in ovarian cancer cells treated with carboplatin, specifically by BMP2 secretion." (PMID 37688374, 2023). "Ishikawa cells secreted higher amounts of BMP2 compared with ovarian cancer cell lines." (PMID 34360647, 2021). "Considering that the expression patterns of BMP receptors were similar between EC and ovarian cancer cells, they may share a common response to BMP2 stimulation." (PMID 34360647, 2021). "For example, MSCs in ovarian cancer increased the proportion of CSCs by secreting BMP2." (PMID 34001269, 2021). "Additionally, T-MSCs promoted the proportion of CSCs, as observed in ovarian cancer cell, probably because of upregulation of bone morphogenetic proteins (BMPs), such as BMP2, BMP4, and BMP6 in ovarian cancer-derived MSCs." (PMID 31555593, 2019).
ovarian carcinoma (continued). "There are only a few reports on the correlation of BMP-2 and ovarian cancer." (PMID 20587070, 2010). "BMP-2, BMPRIB, and BMPRII exhibited low expression in EOC tissue, and variation or loss of expression may indicate poor prognosis for ovarian cancer patients." (PMID 20587070, 2010). "BMP-2, BMPRIB, and BMPRII may play a part in the occurrence and development of ovarian cancer, and the variation or loss of expression of BMP-2, BMPRIB, and BMPRII may be an indicator of poor prognosis for ovarian cancer patients." (PMID 20587070, 2010). "We analyzed the association between patient outcome and BMP-2 protein expression by immunohistochemistry (IHC) using a tissue microarray of clinical samples from 89 ovarian cancer patients that was previously used to determine the potential of BMP-2 as a tumor marker." (PMID 19366455, 2009). "In this study we attempted to clarify the role of BMP-2 in ovarian cancer." (PMID 19366455, 2009). "Consequently, these cell lines appear to be a good model to study BMP-2 effects on ovarian cancer cells." (PMID 19366455, 2009). "In line with this hypothesis, we observed that BMP-2 stimulates the in vitro migration of ovarian cancer cell lines." (PMID 19366455, 2009). "In the present study, we focused on the role of BMP-2 in ovarian cancer." (PMID 19366455, 2009). "We also estimated the performance of BMP-2 as an individual marker of ovarian cancer." (PMID 16421595, 2006). "Previous studies have also associated BMP2 and BMP4 with ovarian cancer, both of which are expressed at extremely low levels in tumor cells and TAMs, which may be explained by the previous identification of ovarian cancer-associated mesenchymal stem cells as a major source of these cytokines." (PMID 27215396, 2016). "Our study suggests that BMP-2 and its receptors BMPRIB and BMPRII are likely to be involved in the development of ovarian cancer, and attenuation or loss of expression may result in or indicate poor prognosis for ovarian cancer patients." (PMID 20587070, 2010). "Soda has reported that BMP-2 can inhibit the growth of cancer cell clones in 2 of 15 ovarian cancer patients, but no study has investigated the influence of BMP-2 on prognosis for ovarian cancer patients or the underlying mechanisms behind its role in the development of ovarian cancer." (PMID 20587070, 2010). "This study was designed to determine the expression of BMP-2 and its receptors in epithelial ovarian cancer, benign ovarian tumors, and normal ovarian tissue and to analyze their influence on the five-year survival rate and average survival time of ovarian cancer patients." (PMID 20587070, 2010). "We examined whether BMP-2 affects cellular proliferation of ovarian cancer cells." (PMID 19366455, 2009). "Our results support this idea but do not rule out the idea that Msln may be an appropriate ovarian cancer marker in association with other markers, such as BMP-2, that complement staining in low-grade endometrioid and clear cell tumours." (PMID 16421595, 2006). "The expressions of BMPs and their signaling components, BMP-2/7, ALK2/3, BMPR-II, and phosphorylated Smad5, are elevated in ovarian cancers." (PMID 35693928, 2022). "Increased levels of bone morphogenetic proteins (BMPs), including BMP2, BMP4, and BMP6 in ovarian cancer derived-MSCs can promote the development of CSCs." (PMID 33685452, 2021). "However, the correlation between BMP-2 and ovarian cancer remains unclear." (PMID 20587070, 2010). "Immunohistochemistry was used to determine the expression of BMP-2 and its receptors in 100 patients with EOC to analyze their influence on the five-year survival rate and survival time of ovarian cancer patients." (PMID 20587070, 2010). "The relative content of the proteins BMP-2, BMPRIB, and BMPRII in ovarian cancer tissue was significantly lower than those in benign ovarian tumors or normal ovarian tissue." (PMID 20587070, 2010).
ovarian carcinoma (continued). "The mRNA expression levels of BMP-2, BMPRIB, and BMPRII in ovarian cancer tissues was significantly lower than those in benign ovarian tumors or normal ovarian tissue." (PMID 20587070, 2010). "Positively stained BMP-2 and its receptors BMPRIA, BMPRIB, and BMPRII were mainly located in the cytoplasm of ovarian cancer cells and appeared as light brown and brown particles." (PMID 20587070, 2010). "In addition, supernatants of primary cultures of cancerous cells showed higher concentrations of BMP-2 than supernatants from NOSE cells demonstrating that an active mature form of BMP-2 is expressed by ovarian cancer cells and could be release in the microenvironment." (PMID 19366455, 2009). "In addition, we found that Ishikawa cells secreted BMP2 at a higher level than OVSAHO and SKOV3 ovarian cancer cells, as determined by an ELISA." (PMID 34360647, 2021). "BMP2, 5 and rhBMP9 has been reported to be involved in RAS-MAPK mediated pathway that activates p65 cytokine and during tumorigenesis and thus proliferate ovarian cancer." (PMID 31973134, 2020). "Our evidence suggests that the weakening of the inhibitory effect of BMP-2 and BMPRIB may promote the development of ovarian cancer." (PMID 20587070, 2010). "Since BMP-4 shares the same receptor with BMP-2, BMP4 may show effects similar to those seen with BMP-2, and therefore we also examined Snail expression, a BMP-4 regulated gene in ovarian cancer cells." (PMID 19366455, 2009). "In ovarian cancer cells, BMP2 promotes cell proliferation and self-renewal capacity via c-Kit induction as well as cell migration and invasion via EMT; these effects are TNFRSF12A/FN14-dependent, as silencing of FN14 suppresses BMP2 actions in ovarian cancer cells." (PMID 38256140, 2024). "Two other comparative studies have indicated that low expression and absence of BMP2 might be related to progression to a more aggressive phenotype in PCa and signal poor prognosis of patients with ovarian cancer." (PMID 37118847, 2023). "Furthermore, the gene expression profiling of cancer-associated MSCs demonstrated the potential roles of transforming growth factor-β (TGF-β) superfamily/bone morphogenic protein (BMP) family members, specifically BMP2, BMP4, and BMP6, in the promotion of ovarian cancer progression." (PMID 30568223, 2019). "This suggests that BMP-2 may act through its receptors, BMPRIB and BMPRII, in ovarian cancer." (PMID 20587070, 2010). "The biological role of BMP-2 in ovarian cancer has not been elucidated." (PMID 19366455, 2009). "Immunohistochemistry results demonstrated that ovarian cancer patients with positive expression of BMP-2, BMPRIB, and BMPRII exhibited remarkably higher five-year survival rates and average survival rates than patients with negative expression of BMP-2, BMPRIB, and BMPRII." (PMID 20587070, 2010).